PECAM1 (platelet and endothelial cell adhesion molecule 1)
Diseases named in the same sentence as PECAM1 in open-access papers (continued):
Sharing a sentence is not in itself a finding about the gene and the disease.
tumor (continued). "Quantification of tumor vasculature by PECAM-1 immunostaining showed 59% ±9.3 reduction of vascular area in GKT136901-treated tumors as compared to vehicle treated animals." (PMID 21326871, 2011). "PECAM-1 has been reported to be expressed in certain carcinoma cells and contributes to tumor cell adhesion." (PMID 20074345, 2010). "The data demonstrated that Pyk2 and PECAM-1 were critical mediators of both anchorage-independent growth and anoikis resistance in tumor cells." (PMID 20074345, 2010). "Tumor cell aggregate formation is mediated by PECAM-1 and Pyk2 signal transduction, leading to cell proliferation." (PMID 20074345, 2010). "Since both Pyk2 and PECAM-1 are important in mediating the formation of tumor cell aggregates and promoting the anchorage-independent growth, we used co-immunoprecipitation to investigate possible interactions between PECAM-1 and Pyk2." (PMID 20074345, 2010). "Immunohistochemical analysis of PECAM-1/CD31 in tumor masses clearly showed that the content of blood vessels was much less in DIF-1-containing masses." (PMID 20843378, 2010). "Our data demonstrate that PECAM-1 and Pyk2 are also critical molecules in supporting tumor cell anchorage-independent growth." (PMID 20074345, 2010). "We examined the micro-vessel density in Wnt1 and Her2 tumors by immunohistochemical staining of tumor sections with anti-CD31 antibody, a platelet endothelial cell adhesion molecule (PECAM1) marker." (PMID 20087418, 2010). "After mice were sacrificed, tumour volume was measured, and microvasculature assessed by immunohistochemical staining for platelet endothelial cell adhesion molecule 1 (PECAM-1) expression." (PMID 17958916, 2007). "When tumour micro-vasculature was assessed by PECAM-1 staining, the use of TSA or IFNα alone, decreased micro-vasculature formation by 32% and 53%, respectively." (PMID 17958916, 2007). "A localized disruption in the endothelium of vascular endothelial (VE)-cadherin, α-catenin and platelet endothelial cell adhesion molecule-1 (PECAM-1) occurs at the site of tumor cell penetration, which is restored once the tumor cell completes diapedesis." (PMID 15987459, 2005). "In addition, Vimentin and PECAM1/CD31 were analyzed to further characterize the tumor microenvironment." (PMID 40694103, 2026). "Furthermore, the reduction in the expression of key angiogenic genes (i.e., Pecam1, Vcam1, Flt1, and Kdr) indicates that rifaximin effectively inhibits the angiogenic switch, which is critical for tumor growth and metastasis." (PMID 40724957, 2025). "Among the top 10 down-regulated hub genes, PECAM1 was significantly reduced in tumor tissues." (PMID 40361912, 2025). "The infiltration of immune cells, facilitated by PECAM1, appears to thwart tumor growth." (PMID 40361912, 2025). "Concurrently, the hyperoxic state promotes the normalization of tumor vasculature, partly by upregulating the expression of platelet endothelial cell adhesion molecule-1 (PECAM-1/CD31), which facilitates increased infiltration of immune cells into the tumor site." (PMID 40655149, 2025). "Another notable aspect of our study was the use of a reliable preclinical organoid model of EGC combined with scRNA‐seq data and the finding that IL‐33+ endothelial cells can promote angiogenesis and tumor proliferation in EGC by influencing adhesion molecules (PECAM1, CD34, and KRT17)." (PMID 40860436, 2025). "Additionally, immunized animals exhibited reduced expression of platelet endothelial cell adhesion molecule 1 (PECAM-1) in tumor tissues compared to controls, indicating decreased angiogenesis and tumor progression." (PMID 39081320, 2024). "Moreover, control and thrombocytopenic mice with B16F1 tumors had similar tumor endothelial integrity scores and plasma PECAM-1 levels." (PMID 38493157, 2024). "Finally, we injected EdU four hours before sacrificing the mice and subsequently FACS-sorted PECAM1+/CD45− tumor ECs." (PMID 36933174, 2023).
tumor (continued). "Anti-PECAM-1 antibodies have been reported to inhibit late metastatic progression of various tumors without blocking tumor-platelet and tumor-endothelial interactions, events associated with the initial establishment of metastatic tumor foci." (PMID 36688087, 2023). "In view of the central role of osteoclast in the colonization and proliferation of tumor cells in bone tissue, it is meaningful to explore whether PECAM1 can affect the osteoclast differentiation of mononuclear macrophages." (PMID 37007939, 2023). "In addition, the verification experiment of candidate gene function needs to be further improved to better understand the regulation mode of PECAM1 in the process of tumor bone metastases." (PMID 37007939, 2023). "To assess the impact of macrophage-tumor-vessel interactions on endothelial barrier function, we quantified Platelet Endothelial Cell Adhesion Molecule 1 (PECAM-1) staining and conducted dextran permeability measurements on the vascular vessel within each platform." (PMID 37835577, 2023). "Consistent with this hypothesis, increased tumor-stroma interactions were associated with increased mRNA expression of both ACTA2 and PECAM1." (PMID 36647832, 2023). "Analysis of the tumor environment by confocal microscopy revealed a statistically significant increase in CD31 (platelet endothelial cell adhesion molecule-1, PECAM-1) expression in the xenografts treated with cEV (mean: 9.1 ± 3.5) compared to the NaCl control group (mean: 5.1 ± 1.1) (p = 0.0378)." (PMID 36975533, 2023). "In addition, CD44 can mediate intercellular communications which contribute to tumor cell aggregation, in the way similar to other adhesion molecules such as E-cadherin and PECAM1." (PMID 35680853, 2022). "SPP1 and PECAM1 were found significantly upregulated in tumor tissues." (PMID 36676937, 2022). "Studies have also found that the PECAM-1 protein can promote the endothelial migration of lymphocytes and natural killer cell, which take pivotal roles in eliminating the abnormal cells, such as tumor cells." (PMID 33828969, 2021). "To assess the effect of rec46A9 and rec9F8 on MC38 tumor vascularization, we performed Pecam1 IHC staining and determined the frequency of vascular and lymphatic endothelial cells in tumor cells suspensions using CD45/Pecam1/Pdpn staining of endothelial cells by flow cytometry." (PMID 34572851, 2021). "Phosphosites from immune system-associated proteins (e.g., IL3RA, PECAM1, PTPN1, SIGLEC7, and JUP) showed an overall higher phosphorylation in tumor tissues than in normal adjacent tissues, suggesting enhanced immune signaling is likely to occur during tumor development." (PMID 33953186, 2021). "Tumours treated with extracts of Uncaria tomentosa showed a lower level of angiogenesis compared to vehicle-treated tumours as indicated by the decreased staining of the tumour sections for Factor VIII or PECAM-1 (CD31), which are both markers of endothelial cells." (PMID 33670520, 2021). "In addition, tumor-bearing scaffolds had a higher proportion of endothelial cells (CD45− PECAM1+) and fibroblasts (CD45− PDGFRα+) than control scaffolds." (PMID 33782087, 2021). "In our initial analysis, rare non-tumor cells clustered separately from tumor cells, and their identity was further validated by the expression of well-known stromal markers including Vim, Ptprc, Trpm5, Pecam1, Mgp, Cd79a, Itgam, Adgre1, Cd3g, and Marco." (PMID 33821796, 2021). "This hypothesis was further confirmed by the significant increase of angiopoietin 1 and Pecam1 mRNA expression and by histological analysis of Pecam1 staining in apelin‐infused tumours." (PMID 32681609, 2020). "Endothelial cell surface marker genes, CD31 (PECAM1) and von Willebrand factor (VWF), were also significantly elevated in high score tumors (both p < 0.001) indicating that high score is associated with increased concentration of blood vessels inside a tumor." (PMID 32933189, 2020).
tumor (continued). "Then, we measured tumor volume and weight and assessed PECAM1+ vasculature." (PMID 31604908, 2019). "Also, compared to WT mice, lower levels of liver markers (AST, ALT, Bil), cytokines (Tnfα, Tgfβ, Il6), and tumor markers (c-Myc, Mmp2, Epcam) in Pecam-1-deficient mice after TAA-application underline the important functions of PECAM-1." (PMID 31344919, 2019). "However, we found that embolization with the degradable embolic particles (EMB) inhibited tumor angiogenesis, as indicated by a reduced number of PECAM-1-positive cells." (PMID 31601175, 2019). "In briefly, CD300A may contribute to tumor proliferation and apoptosis by upregulating PECAM1 and ADCY7, in addition to recruiting PTP in AML cells." (PMID 29938007, 2018). "The expression of PECAM1/CD31 correlated negatively with tumour size and grading." (PMID 26044849, 2015). "Here, we could show that tumour cells were mainly located adjacent to PECAM-1 positive blood vessels in fibrotic livers, further highlighting the role of PECAM-1." (PMID 24734240, 2014). "However, the improvement of the delivery system of siRNACD31 for achieving complete dissolution of the tumor xenografts with siRNACD31 mediated by lipoplexes and the regulation mechanism of PECAM-1 on VEGF requires further exploration." (PMID 24959215, 2014). "The endothelial specific marker, PECAM-1 (i.e., CD31), is closely associated with angiogenesis, and the vasculature of the TME plays a significant role in the proliferation and invasion of tumor cells." (PMID 24959215, 2014). "On the other hand, blockade of PECAM-1 could be beneficial regarding tumour growth and metastasis in the fibrotic liver." (PMID 24734240, 2014). "Because proangiogenic growth factors released from platelet granules could affect tumor vessel formation, we examined vessel density and coverage in the tumors by using anti-PECAM-1 and anti-α–SMA double staining." (PMID 24606812, 2014). "Immunohistochemical analysis of the vessel associated markers murine PECAM-1/CD31 and laminin showed an obvious shift from initial tumor vascularization (HUH-wt), as it is typical for HUH7 xenografts, to a tumor tissue with a decreased murine vessel density (HUH-REISO) at the therapy endpoint." (PMID 23547746, 2013). "Moreover, the analysis of PECAM-1 expression revealed a reduction of the number of tumor blood vessels by ~50 % after HAI of CE plus BE." (PMID 23187934, 2013). "To evaluate whether the perlecan-null ES cells also contributed to the tumor vasculature, we double immunostained perlecan-null teratomas with PECAM-1 and perlecan antibodies." (PMID 23320101, 2013). "Furthermore, RNA interference-mediated reduction of Pyk2 and PECAM-1 protein levels reduced cell aggregation and inhibited the growth of tumor cells in soft agar." (PMID 20074345, 2010). "We have identified a novel physical interaction between PECAM-1 and Pyk2, which could play an important role in tumor cell aggregate formation in suspension cultures and in aggregate-dependent proliferation." (PMID 20074345, 2010). "Furthermore, knockdown of PECAM-1 expression decreased the size of tumor cell aggregates and their colony-forming ability." (PMID 20074345, 2010). "Moreover c-MYC induces production of VEGF by tumor cells leading to tumor vascularisation with unusual vessels that are mosaics containing PECAM-1 positive and PGP 9.5 positive endothelial cells." (PMID 19551151, 2009). "Similarly, a high level of PECAM1 (CD31) in tumour tissues (275.0 ± 73.7), compared with normal background tissues (145.7 ± 30.0), p = 0.8." (PMID 16430777, 2006). "This suggests that higher PECAM1 expression may be indicative of reduced tumor progression." (PMID 40361912, 2025). "In addition, we evaluated PECAM1 levels in both subcutaneous and orthotopic tumor tissues." (PMID 39477683, 2025).
tumor (continued). "The results indicated that sh-PECAM1 treatment could promote osteoclast differentiation, and the sh-PECAM1-treated osteoclast culture medium could significantly promote the proliferation and migration of tumor cells." (PMID 37007939, 2023). "Accordingly, tumor cells were extracted for subpopulation analysis, and the identified malignant cells clustered into eleven subclones: BRCA_SRGN, BRCA_SLC39A6, BRCA_ITGB3, BRCA_PECAM1, BRCA_PPP1R1B, BRCA_VCAM1, BRCA_ICAM1, BRCA_S100A9, BRCA_GLUL, BRCA_TASTD2 and BRCA_AGR3." (PMID 37626402, 2023). "The results indicated that PECAM1 gene might play a role in promoting osteoclast differentiation and tumor cell proliferation and migration in bone, which provided a new entry point for the diagnosis and treatment of bone metastases of tumor." (PMID 37007939, 2023). "Previous works reported that knockdown of PECAM1 expression in mononuclear cells could lead to the enhanced osteoclast differentiation, which suggested that PECAM1 might regulate bone metastases of tumor by affecting osteoclast differentiation." (PMID 37007939, 2023). "Thus, we conjectured that the low expression of PECAM1 might exert influence on anti-tumor immunity in the LUAD microenvironment." (PMID 33461176, 2021). "PECAM-1 is expressed by some tumor cells and may contribute to tumor invasion." (PMID 33828969, 2021). "Interestingly, PECAM1 staining revealed a significantly diminished microvascular density (MVD) in RPMI-8226 tumor masses from macitentan-treated mice, as compared to controls, thus suggesting that in MM macitentan could also exert an anti-angiogenic activity." (PMID 33489901, 2020). "Therefore, we examined the mRNA expression of different specific markers corresponding to cancer-associated fibroblasts (CAF) (Acta2, coding alpha-SMA), endothelial cells (EC) (Pecam1, coding for CD31), and tumor-associated macrophages (TAM) (Adgre1, coding for F4/80)." (PMID 32438553, 2020). "Indeed, leukocytes require a number of molecules in order to roll, adhere, and finally transmigrate into the tumour microenvironment, including selectins, PECAM-1, intracellular adhesion molecular-1, -2 (ICAM-1, ICAM-2, respectively), and vascular cell adhesion molecular -1 (VCAM-1), amongst others." (PMID 31212986, 2019). "Furthermore, tumor volume and immunostaining for proliferation marker Ki67 decreased, whereas staining for vascularity marker, platelet and endothelial cell adhesion molecule 1 (PECAM1; alias, CD31) remained unchanged." (PMID 30241339, 2018). "A significantly high PECAM1 expression level was observed in the non-PD group, suggesting that the vascular density of the tumor might be associated with the response to sorafenib." (PMID 26046304, 2015). "In addition, PECAM-1 is located at the cell junctions on endothelial cells and may also contribute to tumour cell arrest and extravasation." (PMID 22272201, 2012). "Individual cases exhibited variations, like higher vimentin with lower FAP and PECAM1/CD31, highlighting tumor morphological heterogeneity and regional adaptability." (PMID 40694103, 2026). "Markers such as CD31 (PECAM1), CD34 and von Willebrand factor are commonly used to identify endothelial cells and differentiate them from tumour cells." (PMID 39865437, 2025). "CD31(Pecam1) and LYVE1(Lyve1) expression in tumor tissues of the orthotopic HCC mouse models were also identified by IHC analysis, which was shown by the representative images." (PMID 40685403, 2025). "As the VEGF pathway is the main signal promoting tumor angiogenesis, we then analyzed the expression correlation between ENH and vascular endothelial‐specific marker PECAM1 (CD31)." (PMID 40536254, 2025). "IL‐33 can upregulate the expression of endothelial adhesion molecules (PECAM1 and CD34) and organoid adhesion molecules (KRT17), thus promoting angiogenesis (cell‐to‐cell adhesion) and tumor proliferation." (PMID 40860436, 2025).
tumor (continued). "The results showed a pattern in which PECAM1, VWF, CXCR4, and CXCL12 appeared to infiltrate regions of the tumor delineated by HE staining and EPCAM." (PMID 39965034, 2025). "Canonical markers were used to annotate different cell types: malignant cells (COL1A1, IBSP), myeloid cells (CD74, CD14), osteoclasts (CTSK, MMP9), pericytes (RGS5, ACTA2), endothelial cells (PECAM1, VWF), and tumor-infiltrating lymphocytes (CD3D, NKG7)." (PMID 40730548, 2025). "Further information flow analysis identified increased expression of PECAM1, EGF, VISFATIN, ANNEXIN, and LAMININ in the high‐ac4C group, molecules known to play critical roles in tumor initiation, progression, and metastasis." (PMID 40767620, 2025). "Overall, AGER, PECAM1, and SLC2A1 were validated for their expression in normal and LUAD tumor IHC samples, showing that the candidate gene biomarkers can function as biologically significant biomarkers to aid in the detection of early-stage LUAD." (PMID 40563443, 2025). "As PECAM1 showed high cS/E ratio of 15.2 like CAFG, tumor angiogenesis was highly specific to cancer str of the CRC tumors." (PMID 38557819, 2024). "Consistent with the clinical tumor, the EHE PDX expressed high levels of ERG and CD31 (PECAM1) transcripts." (PMID 39283723, 2024). "Further, AGTR1 is also involved in regulating immune chemokines, checkpoints and immune regulatory factors such as PECAM1, ADARB1, SPP1 and ENO1, all of them playing important roles in immune cell regulation, tumor cell proliferation and migration." (PMID 39450258, 2024). "In the PC transplantation model, gemcitabine can reduce the protein levels of VEGF, VEGFR2, platelet and endothelial cell adhesion molecule 1 (CD31, PECAM1) and HIF-1α to reduce blood vessel formation, thereby reducing tumor growth." (PMID 38725864, 2024). "Conversely, PECAM1 and CDKN1A were upregulated in tumor tissues but downregulated in groups with higher TNM categories, advanced cancer stages, and grades." (PMID 38802480, 2024). "We further explored specific communication pathways and discovered that signaling via PTPRM, MIF, MK, PECAM1, and SPP1 was markedly more active in the tumor group compared to the normal group." (PMID 39165361, 2024). "As a demonstration of ECs and an indicator for evaluating tumor angiogenesis, CD31 is also known as PECAM1." (PMID 37781036, 2023). "Tumor sections also stained positive for vimentin and CD31 (also known as PECAM1) markers, which suggested a mixed epithelial phenotype, possibly with epithelial-to-mesenchymal transition (EMT)." (PMID 36579622, 2023). "In turn, an increase in tumor vascularity occurs in vivo, and to determine this, treated PDAC were examined for CD31 (PECAM-1) by immunohistochemical (IHC) staining." (PMID 36902166, 2023). "Combined PECAM1 and ACTA2 staining showed similar vessel (PECAM1+) area with similar coverage by pericytes (ACTA2+) in the tumor tissue of both WT and Apold1−/− mice." (PMID 36933174, 2023). "For example, tumor cells showed particularly high expressions of KRT8, KRT18 and TCF7L1, whereas endothelial cells showed particularly high expressions of PECAM1 and VWF.." (PMID 35494058, 2022). "The permeability of tumor vessels was enhanced, as well as the abnormal growth of SMA+ mesenchymal cells within vascular walls, in the R2cKO mice, whereas the number of PECAM1+ECs was decreased, which strongly suggests an EndoMT-like change in TECs." (PMID 35130955, 2022). "Several genes coding for cell adhesion molecules (CAMs), which are involved in tumor angiogenesis (i.e., ICAM1, PECAM1, and VCAM1), were highly expressed by OERCs of MCC cells—especially MCC14/2." (PMID 35205840, 2022). "In terms of its clinical relevance, tumor SMA+PECAM1+ vessels and coverage with SMA+NG2+ pericytes were correlated in tumor vessels in patients who underwent radiotherapy." (PMID 35130955, 2022).